SMARCB1 (SWI/SNF related BAF chromatin remodeling complex subunit B1)
Diseases named in the same sentence as SMARCB1 in open-access papers (continued):
Sharing a sentence is not in itself a finding about the gene and the disease.
tumor (continued). "Analyses of genetic alterations in SMARCB1/SMARCA4 were available for 83% (83/100) of patients (tumor and/or blood)." (PMID 35565313, 2022). "Allele-specific copy number and clonal heterogeneity analysis performed using FACETS estimated a tumor purity of 0.18 and loss of heterozygosity (LOH) via deletion of chromosomes 4, 13, 15, and 22, the latter of which includes the SMARCB1 gene locus." (PMID 35837094, 2022). "Despite one tumor sample failing quality control in both linked-read genome sequencing and RNA-seq, biallelic somatic disruption of SMARCB1 was detected in both parental haplotypes of all the rest tumor samples." (PMID 35806102, 2022). "Intriguingly, SMARCB1-deficient pediatric MRT and RMC have recently been reported to be immunogenic, despite their very simple genome and low tumor mutational burden." (PMID 35327458, 2022). "Loss of SMARCB1 is the most common recurring mutation in these cancers, highlighting the extensive role that SNF5 plays in tumor suppression." (PMID 35650187, 2022). "The identification of novel SMARCB1 interactions has expanded our understanding of how it functions as a tumor suppressor." (PMID 35892904, 2022). "The ATRT subgroups ATRT-TYR, ATRT-SHH, and ATRT-MYC are not only different in regard to their DNA methylation profiles and their transcriptomes, but also harbor different kinds of tumor-driving SMARCB1 alterations." (PMID 33331994, 2021). "Taken together, therefore, factors other than embryological timing of disruption of SMARCB1 would seem to influence tumour formation in humans." (PMID 33658498, 2021). "To demonstrate that nuclear export of Q318X mutant results in inactivation of SMARCB1 tumor suppressor function, we carried out an SMARCB1-mediated senescent cell formation assay in MON cells." (PMID 34003336, 2021). "Overexpression of SMARCB1 in the patient derived AT/RT tumor cells led to significantly reduced HML-2 transcription." (PMID 34945804, 2021). "In Drosophila it has been shown that Snr1, the fly homologue of SMARCB1, is not only of nuclear but also of cytoplasmic location and that cytoplasmic Snr1 exerts tumor suppressive roles by affecting endosomal trafficking of membrane proteins." (PMID 34003336, 2021). "In conclusion, inhibition of nuclear export restores nuclear location and residual tumor suppressor function of truncated SMARCB1." (PMID 34003336, 2021). "We previously found that dysfunctional chromatin remodeling due to loss of SMARCB1 expression induces HML-2 envelope (env) expression, impairing cellular differentiation and migration, and facilitating tumor growth in AT/RT." (PMID 34945804, 2021). "Taken together, the cell culture data indicate that C-terminally truncated SMARCB1 mutants that are cytoplasmically localized due to the unmasking of nuclear export, appear to maintain residual tumor suppressor function when reverted back to the nucleus." (PMID 34003336, 2021). "We show that RT cells are hypersensitive to mithramycin and link the activity to the fundamental genetic lesion of the tumor, SMARCB1 deletion, and consequential aberrant SWI/SNF activity." (PMID 33332735, 2021). "SMARCB1, a potential tumour suppressor gene located at chromosome 22q11.2, is a core component of the SWI/SNF complex that plays a prominent role in several cellular biological behaviours and the development of cancers." (PMID 34668612, 2021). "These subgroups differ in terms of age at diagnosis, tumor location, type of SMARCB1 alterations, and overall survival." (PMID 33331994, 2021). "Collectively, these observations indicate that the formation of the SMARCB1–SMARCC2 subcomplex is required for its subsequent association with SMARCA4 and for tumor suppression." (PMID 33024572, 2020). "In pRCC2 tumors, we observed a SMARCB1 driver mutation in one pRCC2; TERT promoter in two pRCC2; SETD2, PBRM1 and NF2 in one pRCC2 tumor each." (PMID 32555180, 2020).
tumor (continued). "SMARCB1 has been characterized as a potent tumor suppressor with the involvement in the regulation of cell proliferation, apoptosis, and differentiation in the development and progression of tumors." (PMID 33163142, 2020). "SJATRTMYC-17-03885 and SJATRTMYC-17-03886 (derived from the same patient tumor) PDOX models exhibited simultaneous somatic mutation (located in exon 5; E184*) and focal deletion (impacting exons 2–5) of SMARCB1." (PMID 32519082, 2020). "The metastatic samples in pRCC2_1824_13, which most likely originated in the primary tumor region T02 or T10, share the same driver mutations in PBRM1 and SMARCB1." (PMID 32555180, 2020). "The assembly of the subcomplex comprising SMARCB1 and SMARCC2 and/or SMARCC1 is essential for the tumor-suppression function of SMARCB1." (PMID 33024572, 2020). "More and more benign and malignant tumors are being found to have a loss of nuclear INI1 expression, and the list of so-called SMARCB1-deficient neoplasms is expanding." (PMID 32380731, 2020). "We identify SWINGN, a lncRNA interacting with SMARCB1 exclusively in proliferating conditions, exerting a pro-oncogenic role in some tumor types." (PMID 32071317, 2020). "Complete loss or reduced expression of nuclear SMARCB1 (INI-1) was found in five and two neoplasms, respectively." (PMID 31455041, 2019). "The lineage specificity of SMARCB1’s requirement in neural differentiation is relevant in the context of its role as a tumor suppressor." (PMID 31033435, 2019). "From the molecular point of view, this tumor has been shown to have a homozygous SMARCB1 (INI1) deletion in >90% of both the proximal and conventional subtypes, resulting in the complete absence of INI1 protein expression." (PMID 31416195, 2019). "For example, SMARCB1 deficient cells require residual SWI/SNF function, because concomitant loss of SMARCB1 and SMARCA4 blocks tumor development." (PMID 31123059, 2019). "The low-incidence SMARCB1 R377H mutation was detected in one WHO°II IVM and its corresponding tumor recurrence." (PMID 31470906, 2019). "The tumor in the present case mimicked rhabdoid carcinoma with its rhabdoid features and showed a positive expression of SMARCB1." (PMID 30649642, 2019). "(c) Read counts from WGS identify single copy deletion of SMARCB1 in CLF_PEDS0005_T1 indicated by a Tumor/Normal ratio of approximately 0.5 where SMARCB1 is located." (PMID 30860482, 2019). "Immunohistochemical analysis revealed that the round and rhabdoid cells found in the primary tumor were diffusely positive for SMARCB1 and vimentin." (PMID 30649642, 2019). "SMARCB1 is a tumor suppressor that when conditionally inactivated in mice leads to rapid onset of lymphomas or brain tumors." (PMID 30860482, 2019). "In contrast, others have found that both enhancers and super-enhancers show increased levels of H3K27ac upon SMARCB1 reintroduction into null tumor cell lines." (PMID 31033435, 2019). "When adjusted for tumor purity, the estimated number of copies of SMARCB1 for each case was zero copies, consistent with the biallelic deletion of SMARCB1 in all six tumors." (PMID 31835848, 2019). "Within the Ck+Ne−/SNUC group, two tumours were found SMARCB1-deficient and one showed NUT-1 staining in 30–35% of tumour cells." (PMID 29507386, 2018). "In vivo tumor models, inactivation of EZH2 blocked tumorigenesis driven by SMARCB1 loss, completely." (PMID 29625594, 2018). "Wilson and colleagues observed that loss of SMARCB1 (SNF5) triggers EZH2 expression, broad H3K27-trimethylation, subsequent repression of Polycomb target genes finally resulting in tumor formation." (PMID 30138427, 2018). "Inactivation of the SMARCB1 tumour suppressor abrogates this interaction, thereby reducing H3K27ac levels at distal enhancers." (PMID 28262751, 2017).
tumor (continued). "The inability to detect mutant proteins in all tumour cells by immunostaining is likely to be a consequence of the instability of mutant SMARCB1 proteins." (PMID 27921248, 2017). "Biallelic SMARCB1 inactivation has been detected in a multitude of different tumour types and at high frequency in rhabdoid tumours." (PMID 27921248, 2017). "As would be expected, all three models showed a decrease in SMARCB1 staining in the tumor relative to the endothelium." (PMID 27391784, 2016). "Here, the authors show that inactivation of SMARCB1 between E6 and E10 in mice results in tumours that better recapitulate the human phenotype, compared to previously reported models." (PMID 26818002, 2016). "Our data first show that the developmental stage targeted by Smarcb1 inactivation dramatically impacts the type of tumours obtained." (PMID 26818002, 2016). "MRTs are characterized by the biallelic inactivation of the SMARCB1 (INI1/SNF5/BAF47) gene, which encodes a core component of the SWI/SNF complex and is a tumor suppressor." (PMID 27783942, 2016). "Face and neck tumours obtained from heterozygous knockout of Smarcb1 have been suggested to constitute a good mouse model for human extra cerebral RTs." (PMID 26818002, 2016). "SMARCB1 inactivation is prevalent in human atypical teratoid/rhabdoid tumours but a mouse model that accurately phenocopies the human disease is lacking." (PMID 26818002, 2016). "The restoration of SMARCB1 expression in malignant rhabdoid tumor cells leads to cell cycle arrest and cellular senescence." (PMID 27095948, 2016). "IHC studies are typically negative for S-100, neurofilament protein, carcinoembryonic antigen, factor VIII-related antigen and CD-31, and INI-1 (SMARCB1) whose expression is lost in tumor nuclei." (PMID 26347853, 2015). "These are however a genetically homogeneous group of tumours sharing the underlying biallelic inactivation of SMARCB1, which encodes the SMARCB1/hSNF5/BAF47 subunit of the SWI/SNF chromatin remodelling complex." (PMID 26204834, 2015). "We previously profiled transcriptional changes brought about following re-introduction of Smarcb1 in the same tumor cell line and found enrichment for cytoskeleton and focal adhesion categories already at transcription level." (PMID 26370283, 2015). "Atypical teratoid/rhabdoid tumours (AT/RT) are highly aggressive tumours characterized by biallelic inactivation of the SMARCB1/INI-1/hSNF5/BAF47 tumour suppressor gene." (PMID 26064134, 2015). "To note, there are also many studies showing that reintroduction of wild type SMARCB1 in human AT/RT cells leads to cell cycle arrest and its tumour suppressor function is firmly established." (PMID 26998479, 2015). "Inactivating mutations of the SMARCB1 gene (hSNF5/INI-1) at 22q11.2 is thought to be a crucial step in tumorigenesis, but mutations can be identified in only about 76% of CNS ATRT tumor samples." (PMID 22988546, 2012). "They aimed to correlate cell line and animal data with primary tumor samples, because there had been previous contradictions regarding the relationship between SMARCB1, p16INK4A, and cyclin D1." (PMID 22988546, 2012). "The overall similarity in tumor burden among these conditions is striking given the diverse functions of the NF1, NF2, and SMARCB1 tumor-suppressor genes." (PMID 22558206, 2012). "Histologically, PDC tumours exhibited large polygonal/epithelioid cells or chubby spindle cells, with positive staining for cytokeratins and brachyury, but loss of expression of SMARCB1 (INI1) protein, and a high Ki-67 index." (PMID 42293322, 2026). "However, recent advances in tumor genomics have refined RCC classification, highlighting rare molecular subtypes such as TFE3-rearranged and SMARCB1-deficient RCCs." (PMID 41743914, 2026). "Although cyclophosphamide is not typically used to treat RMC, the loss of SMARCB1 is known to increase replication stress, rendering tumor cells susceptible to alkylating agents such as cyclophosphamide." (PMID 40951353, 2025).
tumor (continued). "Intriguingly, studies suggest that SMARCB1, a recognized tumor suppressor gene in various cancers, may play a significant role influencing sensitivity to EGFR-TKI-based therapy in malignant rhabdoid tumors (MRT)." (PMID 39971779, 2025). "Indeed, biallelic SMARCB1 inactivation is prevalent in these tumours; other frequently recurring genomic changes including deletions, duplications and pathogenic variants are not observed." (PMID 40794298, 2025). "CRINET should be easy to distinguish based on light microscopic evaluation alone, as this tumor is a non-Rhabdoid neuroectodermal tumor with loss of SMARCB1 expression." (PMID 41374972, 2025). "With the advancement of molecular techniques, the histologic diagnosis of AT/RT has been increasingly supported by methods such as next-generation sequencing, deletion/duplication analyses, and tumor microarray testing to detect and confirm SMARCB1 or SMARCA4 alterations." (PMID 41374972, 2025). "As pathologists, molecular geneticists, and physician scientists worked to precisely identify this tumor and differentiate it from its clinical, imaging, and histologic mimics, SMARCB1 (INI-1) immunohistochemistry proved to be a valuable diagnostic tool to diagnose AT/RT." (PMID 41374972, 2025). "The strikingly different tumour phenotypes in patients with SMARCB1-related SWN as compared to patients with RTPS1 indicate that the types and consequences of germline pathogenic SMARCB1 variants must be different between these patient groups and will affect different tumour precursor cells." (PMID 40794298, 2025). "Tazemetostat (an EZH2 inhibitor) was initiated to target the SMARCB1 deletion in the tumor." (PMID 40052132, 2025). "The close interaction between residues W281 and I315, as shown by structural modeling, and its role in protein function highlight its role in SMARCB1’s tumor suppressor activity through stabilization of the SWI/SNF complex (particularly the cBAF and PBAF subcomplexes)." (PMID 40196006, 2025). "The incidence of SMARCB1 gene deletions varies depending on the tumor type and anatomical location." (PMID 40366517, 2025). "Furthermore, it is unusual that a relatively simple recurrent molecular alteration, such as bi-allelic inactivation of SMARCB1 produces a tumor with quite diverse morphologic features and clinical heterogeneity." (PMID 41155355, 2025). "In addition to its role as a tumour suppressor, the SMARCB1 protein is also an important regulator during development." (PMID 40794298, 2025). "Therefore, in the subsequent sections of this article, we will review the molecular functions of SMARCB1, the tumor occurrence mechanisms mediated by it, and related signaling pathways to identify potential therapeutic approaches." (PMID 40115023, 2025). "Initial tumor molecular testing used an adult malignancy-focused panel, which incorporates SMARCB1." (PMID 40036664, 2025). "Growing insights into SMARCB1 biology and epigenetic vulnerability offer promising avenues for targeted therapies, underscoring the importance of reporting additional cases to refine our understanding of this emerging tumor entity." (PMID 41561296, 2025). "In addition to its role as a tumour suppressor, SMARCB1 also plays an important role during neurodevelopment [reviewed by 44]." (PMID 40794298, 2025). "SWN-related hybrid tumours are characterized by a typical mosaic staining pattern of protein SMARCB1 (positive and negative nuclei) and a remarkable loss of LZTR1 (only few positive nuclei left) in LZTR1-SWN." (PMID 41247561, 2025).
tumor (continued). "This may be explainable by the upregulation of EZH2 in SMARCB1-deficient tumours, which enhances CXCR4 expression through the repression of the tumour-suppressive microRNAs miR-622 and miR-9." (PMID 40422882, 2025). "The tumor cells showed a preserved expression of SMARCB1 (INI1) and SMARCA4." (PMID 40988318, 2025). "Notably, genes such as PLAC8 and the Notch ligand JAG2 were significantly upregulated, while tumor suppressors, like SMARCB1, showed marked downregulation." (PMID 41595423, 2025). "Owing to the increased risk of malignancy in patients with SMARCB1-related SWN, it has been recommended that a growing tumour, especially one causing increasingly severe functional impairment, should be immediately investigated for possible malignant transformation." (PMID 40794298, 2025). "These mice did not develop tumours indicating that Smarcb1 loss during later stages of development is on its own not tumorigenic (see Sect." (PMID 40794298, 2025). "In Case 7, SMARCB1 and FANCA variants were detected in the majority of cells (62–92%) in both regions; however, the VAF of an ATR variant (0.28 and 0.13 in Regions A and B, respectively) indicated that this was a later event in the development of this tumour." (PMID 39766052, 2024). "Treatment with CBP/p300 dual inhibitors suppresses growth of cell lines and tumor xenografts derived from SMARCB1-deficient cells but not from SMARCB1-proficient cells." (PMID 38839769, 2024). "SMARCB1 KD also impaired tumor growth in vivo using a xenograft model." (PMID 38472198, 2024). "Tumor xenografts maintained SMARCB1 KD throughout the experiment as shown by SMARCB1 IHC." (PMID 38472198, 2024). "To test this hypothesis, we sought to elucidate the impact of SMARCB1 loss and subsequent STAT3 pathway activation on bladder orthotopic tumor growth, metastasis, and BLCA disease-specific survival." (PMID 38355560, 2024). "Tumor cells with loss of SMARCB1 demonstrate a constitutive EZH2 activation, and EZH2 inhibitors may modulate tumor immunogenicity and anti-tumor immune response." (PMID 38217715, 2024). "Genomic studies have revealed mutations in genes such as SETD2, CDKN2A, SMARCB1, and NF2, which may contribute to the tumor's aggressive phenotype." (PMID 39310439, 2024). "Similarly, to the orthotopic SMARCB1 KO xenografts, the SMARCB1-deficient PDX model demonstrated a significant inhibition of tumor growth with TTI-101 compared to vehicle treatment." (PMID 38355560, 2024). "Numerous drugs aimed at these mutations have demonstrated encouraging outcomes in preclinical tumor models and clinical advancements include FDA-approved EZH2 inhibitors for cancers with SMARCB1 mutations and more targets are now identified through genome-wide screens for clinical trials." (PMID 39348027, 2024). "Loss of SMARCB1 expression leads to ATRTs without the side-effect of massive genomic instability that is observed with some tumour types." (PMID 37433987, 2023). "Furthermore, it has also been shown that, for SMARCB1-deficient RMC, differences in the tumor cell origin make it difficult for physicians to grasp the immune profile of the tumor." (PMID 37367052, 2023). "More potential LM progression-related markers were detected in CSF samples than in tumor samples, including PREX2 mutation (P = 0.014), IGF1R mutation (P = 0.034), AR mutation (P = 0.038), SMARCB1 deletion (P < 0.001), SMAD4 deletion (P = 0.0034), and TGF-beta pathway aberration (P = 0.0038)." (PMID 37131253, 2023).